HOTAIR (HOX transcript antisense RNA)
Diseases named in the same sentence as HOTAIR in open-access papers (continued):
Sharing a sentence is not in itself a finding about the gene and the disease.
glioma (continued). "While actual experimental data are needed to confirm these findings and to identify the exact molecular players and pathways linking HOTAIR and glioma development, other in silico studies have also been conducted to propose the multimodal tumor-promoting activities of HOTAIR in gliomas." (PMID 38366205, 2024). "Thus, transient receptor potential melastatin 7 (TRPM7) channels-induced and HOTAIR upregulation-mediated silencing of miR-301a-3p was found to culminate into significant elevations in the levels of FOSL 1 in glioma tissues." (PMID 38366205, 2024). "Lastly, regulatory elements of HOTAIR gene were observed to determine temozolomide resistance in U251 glioma cells, possibly via expressional modulation of distant genes, calcium binding, and coiled-coil domain 1 (CALCOCO1) and zinc finger CCCH-type containing 10 (ZC3H10)." (PMID 38366205, 2024). "Indeed, data obtained from human glioma tissues as well as U251 and U87 glioma cell lines show aberrant overexpression of HOTAIR and the consequent trans-silencing of miR-141." (PMID 38682637, 2024). "Hence, glioma tissue samples and cell lines elicit aberrantly elevated levels of HOTAIR in complementation with significantly repressed levels of miR-218." (PMID 38366205, 2024). "Similarly, RNA-seq data from Chinese clinical cases of different grades of gliomas indicated HOTAIR as the top upregulated lncRNA, possibly as a consequence of alterations in its epigenetic DNA methylation pattern." (PMID 38366205, 2024). "Finally, we also summarize the results from the studies incriminating HOTAIR in the pathogeneses of gliomas and other brain cancers." (PMID 38682637, 2024). "Although it is clear that HOTAIR is a pro-oncogenic lncRNA which detrimentally affects the pathogeneses of gliomas at multiple levels and via a plethora of molecular targets, its pathogenic impact during the initiation and progression of other neuronal dysfunctions has largely remained undiscerned." (PMID 38682637, 2024). "Considering its extensive multifaceted pro-tumourigenic roles, numerous groups have suggested that HOTAIR may be a potential target for novel anti-glioma therapeutic strategies." (PMID 38682637, 2024). "Analyses of HOTAIR gene expression, methylation status, and copy number in human glioma cases, such as isocitrate dehydrogenase (IDH)-wild type glioblastoma, support the hypothesis of the former’s positive association with glioma grades." (PMID 38366205, 2024). "Perhaps, smart glioma-targeting nanoplatforms might aid in enhancing the specific targeting of this dominant negative HOTAIR mutant to glioma sites in human cases." (PMID 38366205, 2024). "HOTAIR acts as a sponge for miR-126-5p, leading to increased glutamine metabolism in glioma." (PMID 37161350, 2023). "Hence, HOTAIR can promote glutamine metabolism through the miR-126-5p-GLS axis, which causes tumor progression in glioma." (PMID 37161350, 2023). "HOTAIR is significantly expressed in glioma tissues and activates the expression of NF‐kB, TNFa, MAPK, and other inflammatory signaling pathway‐related proteins to activate the immune response, T cell costimulation, and RNA polymerase II to initiate transcription in glioma." (PMID 37088950, 2023). "In gliomas, HOTAIR mainly promotes cell proliferation and migration, and inhibits apoptosis." (PMID 36924407, 2023). "However, aside from glioma, the role of HOTAIR in the pathogenesis, development, and prognosis of other CNS disorders through the regulation of more signaling pathways has not been clearly explained." (PMID 35813070, 2022). "Studies have shown that HOTAIR promotes development of glioma by inhibiting Mir-326 and further promoting the expression of fibroblast growth factor 1 (FGF1), which plays a significant carcinogenic role in tumorigenesis by activating the MEK1/2 and PT3K/AKT pathways." (PMID 35935338, 2022).
glioma (continued). "Moreover, HOTAIR promoted the development of glioma and the expression of fibroblast growth factor 1 (FGF1), which promotes tumorigenesis by activating the PT3K/AKT pathway tumorigenic function." (PMID 35813070, 2022). "Of these, HOTAIR were up-regulated with ascending malignancy grades, and its expression level in high-grade astrocytoma is significantly higher than that in normal brains, suggesting its potential roles in the occurrence and development of gliomas." (PMID 35042456, 2022). "Meanwhile, although the Wnt/β-catenin pathway was also found to be involved in the progression and, thus, the poor prognosis of glioma patients, it is unknown whether HOTAIR plays a role in glioma pathogenesis by regulating the Wnt/β-catenin pathway." (PMID 35813070, 2022). "MiR‐326 has been found to inhibit FGF1 in gliomas by silencing HOTAIR upregulation." (PMID 35592755, 2022). "Furthermore, HOTAIR also impacted the permeability of the blood tumor barrier, by binding to miR‐148b‐3p for the treatment of glioma." (PMID 35592755, 2022). "In glioma, HOTAIR has been found related to the tumor grade, consequence, and molecular subtype." (PMID 35592755, 2022). "Different miRNAs can interact with HOTAIR during glioma progression." (PMID 34576322, 2021). "In addition, HOTAIR aberrantly activated biological processes involved in glioma immune responses, T-cell co-stimulation and transcription initiation by RNA polymerase II." (PMID 34887871, 2021). "We then tested the results of overexpression of HOTAIR in glioma cells treated with AQB." (PMID 34887871, 2021). "HOTAIR regulates the 3’ untranslated region of spindle and kinetochore associated complex subunit 2 (SKA2), and binds the tumor suppressor miR-141 as an endogenous sponge, thus participating in the pathogenesis and progression of human gliomas." (PMID 33980320, 2021). "In glioma tissues, an inverse correlation between miR-141 and HOTAIR expression has been detected." (PMID 33540611, 2021). "In this study, we analyzed the expression of HOTAIR based on the RNA expression database of 702 TGGA glioma patients, analyzed the genes negatively related to HOTAIR expression using bioinformatics analyses and found that many of these genes were involved in tumor formation." (PMID 34082742, 2021). "Similarly, miR-125a-5p is also able to downregulate HOTAIR modulation, through mTOR expression, proliferation, and migration of glioma cells." (PMID 33540611, 2021). "In glioma cells, the expression of lncRNA HOTAIR is abnormally increased." (PMID 33849550, 2021). "HOTAIR has a prognostic role in glioma patients, as a critical regulator of cell cycle progression." (PMID 33540611, 2021). "We further examined the expression of HOTAIR and PPARα in gliomas." (PMID 34082742, 2021). "HOTAIR abnormally activated biological processes involved in the immune response, T cell synergistic stimulation, and RNA polymerase II transcription initiation in glioma." (PMID 34887871, 2021). "More recently, the interaction of HOTAIR and miR-219 has been described in glioma cells." (PMID 34576322, 2021). "Several molecular pathways have been regulated by HOTAIR in glioma." (PMID 34576322, 2021). "Additionally, miR-148b-3p is able to bind HOTAIR, in a sequence-specific manner, suppressing its expression and thereby reducing proliferation, cell cycle progression, and invasion of glioma cells." (PMID 33540611, 2021). "Then, we explored the molecular mechanism by which lncRNA HOTAIR regulates PPARα in cell lines in vitro and in a nude mouse glioma model in vivo and explored the effect of the combined application of HOTAIR knockdown and fenofibrate treatment on glioma invasion." (PMID 34082742, 2021). "HOTAIR silencing induced colony formation suppression, cell cycle G0/G1 arrest and orthotopic tumor growth inhibition, acting as a crucial regulator of cell cycle progression in glioma cells." (PMID 34576322, 2021).
glioma (continued). "Moreover, HOXA9, an oncogenic regulator in glioma, also induced HOTAIR expression via interacting with its promoter." (PMID 34322395, 2021). "Over-expression of HOTAIR has been shown to play a promising role in the occurrence and predictive prognosis of a variety of epithelial-derived malignancies including pancreatic cancer, non-small cell lung cancer, and glioma." (PMID 32700738, 2020). "For example, lncRNA HOTAIR was upregulated in glioma patients and promoted glioma progression through several mechanisms such as acting as ceRNA for miRNA-126-5p and miRNA-326, enhancing angiogenesis, regulating an 18-gene cell cycle-related mRNA network, and activating PI3K/AKT and MEK1/2 pathways." (PMID 33817241, 2020). "In gliomas, HOTAIR was described to promote invasion through upregulation of MMP-7, MMP-9 and VEGF." (PMID 33375038, 2020). "Interestingly, HOTAIR is packed into exosomes secreted by glioma cells and transmitted to endothelial cells where it stimulates angiogenesis by increasing the expression of the proangiogenic factor VEGFA." (PMID 35582278, 2019). "HOTAIR is also involved in the angiogenesis modulation of glioma cells." (PMID 31072041, 2019). "Also in this case, the silencing of HOTAIR in glioma cells dramatically decreases VEGFA expression affecting proliferation, migration and tube formation." (PMID 31072041, 2019). "Together, our data suggest an association between methylation and HOTAIR’s expression in GBM patients and glioma cell lines, but other mechanisms may be crucial in reactivating HOTAIR in these tumors." (PMID 29644006, 2018). "Importantly, HOTAIR was frequently co-expressed with HOXA9 in high-grade gliomas from TCGA, Oncomine, and our Portuguese and French datasets." (PMID 29644006, 2018). "We show that HOTAIR is overexpressed in a subset of high-grade gliomas, particularly in GBMs." (PMID 29644006, 2018). "Previous observations from our group suggested HOXA9 as a possible regulator of HOTAIR in glioma." (PMID 29644006, 2018). "Similarly to GBM, we found for the first time an association between high HOTAIR expression levels and shorter OS in grade III glioma patients with high HOTAIR expression (p = 0.002, Log-rank test)." (PMID 29644006, 2018). "In addition, in a study of glioma stem cells, we also found that HOTAIR can recruit and enrich EZH2 and LSD1 proteins." (PMID 29411538, 2018). "HOTAIR (HOX transcript antisense intergenic RNA) has been reported to be up-regulated in gliomas." (PMID 29137410, 2017). "Collectively, these results suggest that HOTAIR may potentiate glioma development in many facets; thus, it is worthy of further investigation." (PMID 28293170, 2017). "Furthermore, we examined the expression of SNORD47, GAS5, HOTAIR in 124 clinical glioma specimens of different grades: WHO grade I/II (n=40), grade III (n=48), and grade IV (n=36)." (PMID 28410200, 2017). "Similarly, increased expression of NEAT1, HOTAIR, and MALAT1 was also found associated with poor prognosis in glioma." (PMID 29138748, 2017). "To validate whether HOTAIR is target of miR-141 in U87 and U251 glioma cells, we constructed luciferase reporter plasmid containing 3′UTR for HOTAIR." (PMID 27121316, 2016). "Similarly, the inhibition of glioma cells invasion mediated miR-141 mimic was in part rescued HOTAIR." (PMID 27121316, 2016). "In addition, HOTAIR promotes cell cycle progression in glioma as a result of the binding of its 5′ domain to the PRC2 complex." (PMID 27121316, 2016). "Hence, the downregulation of HOTAIR by miR-141 was directly dependent on the recognition site in the HOTAIR 3′UTR in glioma cells." (PMID 27121316, 2016). "Finally, both overexpression of miR-141 and knockdown of HOTAIR in a mouse model of human glioma resulted in significant reduction of tumor growth in vivo." (PMID 27121316, 2016).
glioma (continued). "Furthermore, our analyses demonstrated that miR-141 inhibited the proliferation and invasiveness of glioma cells, whereas HOTAIR reversed the effects that miRNA-141 exerted." (PMID 27121316, 2016). "Next, we investigated whether HOTAIR mRNA expression was inversely correlated with levels of miR-141 in glioma tissues." (PMID 27121316, 2016). "We examined expression of HOTAIR mRNA in human glioma samples." (PMID 27121316, 2016). "Here, we presented strong evidence that miR-141 could inhibit the expression of HOTAIR by combining directly to the 3′UTR of HOTAIR in glioma cells, and an inverse correlation between miR-141 and HOTAIR expression in glioma tissues." (PMID 27121316, 2016). "Because HOTAIR could upregulate SKA2, we next examined whether HOTAIR was co-expressed with SKA2 in human glioma samples." (PMID 27121316, 2016). "Furthermore, HOTAIR was identified as the target of miR-326, and miR-326 mediated the tumor-suppressive effects of HOTAIR knockdown on glioma cell lines." (PMID 26183397, 2015). "Introduction of the HOTAIR 5′ domain in human glioma-derived astrocytoma induced β-catenin." (PMID 25823657, 2015). "Knockdown of HOTAIR exerted tumor-suppressive function in glioma cells." (PMID 26183397, 2015). "In brief, the miR-326 over-expression induced by the knockdown of HOTAIR could down-regulate the FGF1 expression that acted as an oncogenic factor in human glioma." (PMID 26183397, 2015). "Furthermore, knockdown of HOTAIR combined with miR-326 over-expression enhanced the tumor-suppressive effects of HOTAIR knockdown on glioma cell lines." (PMID 26183397, 2015). "Our findings provided solid evidence for the HOTAIR functional role in human glioma." (PMID 26183397, 2015). "The HOTAIR-mediated mechanism that regulates cell cycle progression via these two complexes in glioma cells remains unknown." (PMID 25428914, 2015). "Furthermore, HOTAIR expression was positively correlated with the histopathological grades of gliomas." (PMID 26183397, 2015). "Although lysine specific demethylase 1 (LSD1) and polycomb repressive complex 2 (PRC2) have been demonstrated to be functional targets of HOTAIR, how HOTAIR regulates glioma cell cycle progression remains largely unknown." (PMID 25428914, 2015). "Thus, we demonstrate that in glioma cells, HOTAIR promotes cell cycle progression in an EZH2-dependent manner." (PMID 25428914, 2015). "Our present study showed that HOTAIR expression was up-regulated in human glioma tissues and cell lines, suggesting that HOTAIR may be critically involved in the development of glioma." (PMID 26183397, 2015). "This study identifies HOTAIR as a cell cycle-regulating lncRNA that is essential for glioma cell proliferation, indicating that HOTAIR might be a critical player in cell cycle progression in glioma cells." (PMID 25428914, 2015). "However, it is unclear whether HOTAIR is involved in the regulation of inflammation and immune escape in glioma cells." (PMID 34887871, 2021). "Interestingly, HOTAIR intragenic CpGs were found to be mostly methylated in untreated glioma cells." (PMID 29644006, 2018). "Silencing HOTAIR by siRNA could rescue the expression of miR-326 in human glioma cells." (PMID 28404923, 2017). "Additionally, HOTAIR can affect the malignant biological behavior of glioma by targeting miRNA." (PMID 28187439, 2017). "However, whether HOTAIR is also involved in cell cycle regulation in glioma cells remains undetermined." (PMID 25428914, 2015). "In addition, the HOTAIR knockdown could up-regulate miR-326 that were lowly expressed in the glioma tissues and cell lines." (PMID 26183397, 2015). "Knockdown of HOTAIR could suppress the malignant behaviors of glioma cells." (PMID 26183397, 2015). "According to the study, HOTAIR’s 5′ domain binds to the PRC2 complex, promoting glioma cell cycle progression." (PMID 41439968, 2025).
glioma (continued). "Through the miR‐126/GLS pathway, the lncRNA HOTAIR modulates GLS expression, ultimately impacting the glutamine metabolism process in gliomas and promoting tumor growth." (PMID 40567251, 2025). "Thus, HOTAIR-miR-126-5p-GLS signaling may have significant effects on multiple aspects of glutamine metabolism, aberrant angiogenesis, cellular invasiveness, and temozolomide resistance (see also “HOTAIR as a Mediator of Chemoresistance in Gliomas” section) in glioma pathophysiology." (PMID 38366205, 2024). "Indeed, the expression of HOTAIR may serve as glioma grade predictor and prognostic biomarker." (PMID 38366205, 2024). "As a competitive endogenous RNA of miR-126-5p, upregulated HOTAIR led to decreasing expression of glutaminase (GLS), thereby inhibiting glutamine metabolism and enhancing the malignancy of glioma." (PMID 39539540, 2024). "With regards to CNS cancers, cisplatin has been shown to retard EMT in glioblastoma and neuroblastoma cells, possibly by its ability to alter HOTAIR signalling (Ref." (PMID 38682637, 2024). "By sponging miR‐141, HOTAIR reduced the expression of SKA2, thus suppressing tumor growth in glioma." (PMID 35592755, 2022). "Moreover, HOTAIR may regulate the gene transcription of key repressors of the NF-κB activation pathway through epigenetic regulation, thus participating in the immune escape of glioma cells." (PMID 35813070, 2022). "In gliomas, expression of HOTAIR has been shown to be driven by the BET protein BRD4, and BET inhibitors can reduce expression of HOTAIR." (PMID 35406676, 2022). "Therefore, we concluded that HOTAIR might regulate the gene transcription of key repressors of the NF-κB activation pathway through epigenetic modulation, thereby participating in the immune escape biological process in glioma cells." (PMID 34887871, 2021). "HOTAIR also downregulated tumor suppressor programmed cell death 4 (PDCD4), leading to increased growth and proliferation of glioma stem cells." (PMID 34322395, 2021). "HOTAIR regulated cell cycle progression in glioma cells via interactions with EZH2, and inhibition of HOTAIR repressed glioblastoma tumor growth in vivo." (PMID 34316694, 2021). "It has been found that in pancreatic cancers, HOTAIR-mediated gene repression is both PRC2-dependent and independent; however, in glioma cells, HOTAIR regulates cell cycle progression predominantly via the PRC2 axis (EZH2-dependent)." (PMID 30866496, 2019). "Further analysis in 4 independent datasets showed a statistically significant correlation between the expression of HOTAIR and HOXA9 in all glioma sets." (PMID 29644006, 2018). "To verify if the frequent co-expression of HOTAIR and HOXA9 in glioma cell lines is present in glioma clinical specimens, we evaluated their expression levels and potential correlations in the Portuguese, French, and TCGA datasets." (PMID 29644006, 2018). "Globally, HOTAIR was highly expressed in GBM, particularly in IDH-wt GBM, as compared to lower-grade gliomas and normal brain." (PMID 29644006, 2018). "In a first approach, we analyzed the expression levels of HOTAIR in grades II and III gliomas, and in grade IV GBM patients using gene expression microarray data and RNA-sequencing (RNA-seq) data from The Cancer Genome Atlas (TCGA)." (PMID 29644006, 2018). "For example, lncRNAs, such as HOTAIR, CRNDE, GAS5 and other lncRNAs with abnormal expression in glioma tissues and cell lines, regulate the biological behaviors of glioma cells." (PMID 29132362, 2017). "Among differentially expressed lncRNAs, we further validated seven lncRNAs (7SL, EGO-A, HOTAIR, JPX, MEG3, RNCR3, and ZFAS1) on a bigger cohort of glioma samples of different WHO malignancy grades and histopathological subtypes." (PMID 29138748, 2017). "It has been shown that HOTAIR can control the expression of Rab 22a by sponging miR-373 in ovarian cancer, and modify miR-141 in regulating SKA2 in glioma." (PMID 29156804, 2017).